NLRP3 (NLR family pyrin domain containing 3)
Diseases named in the same sentence as NLRP3 in open-access papers (continued):
Sharing a sentence is not in itself a finding about the gene and the disease.
breast cancer (continued). "In addition, NLRP3 inhibition proved to be protective against IL-1β upregulation in peritumoral astrocytes in the mouse breast cancer brain metastasis model, resulting in an approximately 75% decrease in the percentage of IL-1β- and GFAP-double-positive pixels." (PMID 37749707, 2023). "Thus, the role of NLRP3 inflammasome in breast cancer may depend on the tumor microenvironment and the subtype of breast cancer." (PMID 37715239, 2023). "Pyroptosis-associated proteins, including NOD-like receptor pyrin domain-containing protein 3 (NLRP3), the apoptosis-associated speck-like protein containing a CARD (ASC), and caspase-1, are overexpressed and are abnormally activated in most cancer types, especially in breast cancer." (PMID 36677797, 2023). "Moreover, NLRP3 inflammasome activation by leptin supplementation induced breast cancer growth." (PMID 36794014, 2023). "Considering the reported IL-1β signal reported in breast cancer, we sought to investigate whether NLRP3 activation is involved in the production of IL-1β in breast cancer and whether its inhibition would reduce the increased IL-1β signal and enhance anti-PD-1 therapy." (PMID 35631400, 2022). "However, DPP inhibitors also promoted the recruitment of tumor-infiltrating CD45, MPO, F4/80, CD4, Foxp3-positive cells, and MDSC and decreased CD8-positive lymphocytes in metastatic sites in mouse breast cancer models by ROS-NF-κB-dependent NLRP3 inflammasome activation." (PMID 35739593, 2022). "Furthermore, CASP8 (2%), NLRC4 (1%), NLRP3 (1%), NLRP2 (1%), PLCG1 (1%), NLRP1 (1%), NLRP7 (1%), SCAF11 (1%), GSDMC (1%), and NOD1 (1%) occurred somatic mutations as well as most of them had high frequencies of CNV in breast cancer." (PMID 34589498, 2021). "In this review we focus on the role of NLRP3 inflammasome and its components in breast cancer signaling, highlighting that a more detailed understanding of the clinical relevance of these pathways could significantly contribute to the development of novel therapeutic strategies for breast cancer." (PMID 33840390, 2021). "Notably, NLRP3 inflammasome represents a novel potential target for the treatment of breast cancer." (PMID 34178667, 2021). "NLRP3 inflammasome could represent a novel potential target for the treatment of breast cancer." (PMID 33096896, 2020). "Notably, analysis of pro-inflammatory genes that were upregulated in mammary CAFs using the STRING database of human protein networks, showed enrichment of inflammatory pathways, including NLRP3/IL-1β signalling, confirming the functional connectivity between genes of this pathway in breast cancer." (PMID 31558756, 2019). "In breast cancer, autocrine IL-1β secretion driven by the NLRP3 inflammasome promotes EMT, and metastasis in breast cancer." (PMID 40692785, 2025). "Numerous studies have demonstrated the activation of the NLRP3 inflammasome by LPS+ATP in diverse cell types, including THP-1 macrophages, LX-2 hepatic stellate cells, MCF-12A and MDA-MB-231 breast cancer cells, and A549 non-small-cell lung cancer cells." (PMID 39858497, 2025). "Subsequently, this excessive ROS accumulation triggers the activation of the NLRP3 inflammasome and the secretion of mature cytokines such as interleukin-1β (IL-1β) within the TME, which facilitates breast cancer recurrence and metastasis." (PMID 39472438, 2024). "To prove that astrocyte-conditioned media increased the proliferation of breast cancer cells through inflammasome activation and IL-1β secretion, we treated astrocytes with MCC950, a specific NLRP3 inhibitor." (PMID 37749707, 2023). "Without distinguishing between fibroblasts and macrophages, we found that NLRP3, caspase-1, ASC, IL-1β, and IL-18 were all elevated in the breast cancer immune-stromal cells." (PMID 38031068, 2023). "According to these findings, using NLRP3 and caspase-1 (MCC950 or Ac-YVAD-cmk) inhibitors to treat breast cancer cells can slow their proliferation." (PMID 37715239, 2023).
breast cancer (continued). "But as previously reported, NLRP3 and ASC proteins were both significantly upregulated in invasive ductal carcinoma cells of breast cancer patients." (PMID 38031068, 2023). "As additional proof of inflammasome priming in astrocytes, human brain samples with breast cancer metastases were immunostained for IL-1β, which was also found to colocalize with GFAP and NLRP3 in the peritumoral regions." (PMID 37749707, 2023). "Another coenzyme, Q0 was able to decrease HIF-1α expression, to ameliorate NLRP3-mediated inflammation, and suppress the EMT/metastasis and the metabolic rewiring in breast cancer." (PMID 37819510, 2023). "A previous study discovered that NLRP1, NLRP3, NLRC4, and AIM2 inflammasome complex proteins had pro- or antitumoral properties, especially in breast cancer." (PMID 36437954, 2022). "In particular, via controlling innate and adaptive immunity as well as tumor growth, NLRP1, NLRP3, NLRC4, and AIM2 have an effect on how breast cancer develops." (PMID 36119049, 2022). "In this inquiry, the protein expression of c‐Caspase‐1 in breast cancer cells under DOX treatment was lightly reduced within 24 hours, while the expression patterns of GSDMD‐F, GSDMD‐C IL‐1β and NLRP3 hardly changed." (PMID 34369076, 2021). "On the other hand, NLRP3 and IL-1β expression in TAMs correlated with survival, lymph node invasion, and metastasis in patients with HER2+ breast cancer." (PMID 33840390, 2021). "According to our observations, treatment with inhibitor of NLRP3 inflammasome or caspase-1 (MCC950 or Ac-YVAD-cmk) showed to inhibit breast cancer cells growth in MCF-7 and T47D breast cancer cells." (PMID 32155890, 2020). "The effect of Caspase 1 inhibitor (VX765) and combination of LPS/Nigericin on NLRP3 inflammasome activity was analyzed in A549 (lung cancer), MCF-7 (breast cancer), PC3 (prostate cancer), SH-SY5Y (neuroblastoma), and U138MG (glioblastoma) cells." (PMID 33613529, 2020). "The NLRP3 inflammasome also promotes tumor growth and metastasis in various cancers, such as OSCC, HNSCC, pancreatic carcinoma, and breast cancer." (PMID 31312615, 2019). "The findings suggest that NLRP3 and GSDMD-N expression levels in breast cancer tissues could serve as an indicator of tumor prognosis." (PMID 39744516, 2025). "Studies have shown that NLRP3 and EMT may play an important role for therapeutic resistance in breast cancer." (PMID 41148809, 2025). "Additionally, the observed suppression of NLRP3 inflammasome signaling in SAADKO tumors represents a novel finding, as this study is the first to report such an effect in an in vivo breast cancer model." (PMID 39336082, 2024). "MiR-223 may suppress the development of breast cancer by targeting multiple oncogenic transcripts, including epithelial cell transforming 2 (ECT2), Profilin 2 (PFN2) and NLRP3." (PMID 39125761, 2024). "In the current study, we convert to evaluate the differential expression and clinicopathological features of NLRP3 inflammasome pathway-related proteins, including NLRP3, caspase-1, ASC, IL-1β, and IL-18, in the tumor parenchymal and immune-stromal cells of breast cancer." (PMID 38031068, 2023). "In addition, breast cancer and atrial fibrillation develop through the same inflammatory pathways, such as the NOD-like receptor protein 3 (NLRP-3) inflammasome." (PMID 36970342, 2023). "Macrophage-specific S1PR1 signaling promoted NLR family pyrin domain containing 3 (NLRP3) expression leading to enhanced IL-1β production via the inflammasome, which resulted in enhanced lymphangiogenesis and tumor metastasis in a murine breast cancer model." (PMID 35163211, 2022). "These researches indicate that the high expression and activation of inflammasomes NLRP3, NLRP1, and NLRC4 may promote breast cancer progression including growth, metastasis, and invasion." (PMID 36119049, 2022).
breast cancer (continued). "In addition, the researchers uncovered that the NLRP3 inflammasome promoted the infiltration and metastasis of lymph nodes in patients with HER2+ breast cancer through the lymphatics downstream of S1PR1 signaling in macrophages." (PMID 36119049, 2022). "Conversely, in a mouse model of orthotopic breast cancer, the lack of either NLRP3 or caspase-1 genes resulted in fewer lung metastases, suggesting that the NLRP3 inflammasome is promoting cancer." (PMID 36555392, 2022). "Tumor sizes were similar between WT and Nlrp3 KO mice, indicating that NLRP3 does not support mammary tumor growth in vivo, unlike caspase-1 and ASC." (PMID 33042810, 2020). "There is no direct evidence for NLRP3 inflammasomes in breast cancer; however, indirect evidence implicates a role of inflammasome activation in breast tumour development through IL-1β." (PMID 30447690, 2018). "Moreover, the role of NLRP3 inflammasome in breast cancer may depend on the TME and the subtypes of breast cancer." (PMID 41560727, 2025). "However, the tamoxifen mediated suppression of NLRP3 increased the proliferation of tumor cells lacking ER-α, whilst it attenuated proliferation of ER-α-expressing breast cancer cells." (PMID 36517518, 2022). "Another study has confirmed that pyroptosis induced by NLRP3 and IL-1β secretion might adjust the TME towards an immune suppressive milieu, which facilitates cancer proliferation and invasion in mouse and human breast cancer." (PMID 36119049, 2022). "Moreover, MEG3 was found to promote cisplatin-induced pyroptosis by promoting the NLRP3/caspase-1/GSDMD axis, implying that MEG3 may be an effective therapeutic target for enhancing breast cancer chemotherapy." (PMID 35392086, 2022). "In addition, MEG3 was found to activate cisplatin-induced cellular pyroptosis by promoting NLRP3/caspase-1/GSDMD axis, implying that MEG3 could be effective therapeutic target of breast cancer." (PMID 34488540, 2021). "Remarkably, we found that multiple genes that belong to the NLRP3 inflammasome pathway, including P2rx7, Nlrp3, Casp1, Il1a and Il1b are upregulated in CAFs isolated from mammary carcinoma, but not in normal mammary tissue, or in fibroblasts isolated from mammary hyperplasia." (PMID 31558756, 2019). "However, counteracting neutrophil trafficking (by NLRP3 inhibition) or neutrophil aging (by CXCR2 blockade) attenuated tumor progression, whereas supporting neutrophil aging (by blockade of CXCR4) even enhanced tumor growth in SCC VII HNSCC and 4T1 breast cancer." (PMID 34876407, 2021). "Although NLRP3 mRNA expression levels were increased in RT-R-MDA-MB-231 cells compared to MDA-MB-231 cells, the protein levels were not very different and were not responsive to TNF-α or ATP treatment in either type breast cancer cell." (PMID 32397236, 2020). "Additionally, immunohistochemistry (IHC) of advanced mammary carcinoma tissue sections from MMTV-PyMT mice confirmed that in addition to its activation in tumour cells, NLRP3 is upregulated in CAFs, but not in normal mammary fibroblasts (NMFs)." (PMID 31558756, 2019).
chronic kidney disease (127 papers, 2013 to 2026). Impairment of the renal function secondary to chronic kidney damage persisting for three or more months. "This study investigates the regulatory role of HK1-mediated glycolysis in NLRP3 inflammasome-driven pyroptosis during chronic kidney disease (CKD)-associated vascular calcification (VC) and the protective effects of Irisin/FNDC5." (PMID 41503885, 2025). "The NLRP3 inflammasome is implicated in the pathogenesis and progression of chronic renal failure, according to numerous studies." (PMID 38114914, 2023). "Present-day studies indicate that NLRP3 inflammasome stimulation is associated with the causative pathology of chronic kidney disease (CKD)." (PMID 34443594, 2021). "It was reported that activation of NLRP3 inflammasome had a determining role in increased severity of inflammation associated with dialysis in patients with chronic kidney diseases." (PMID 34904012, 2021). "Curiously, low NLRP3 mRNA levels in renal biopsies were correlated with a high risk of end-stage renal disease and a twofold increase in serum creatinine." (PMID 31694192, 2019). "Our study is the first to extensively characterize NLRP3 in the human kidney and evaluate its expression in the context of IgAN, a common cause of chronic kidney disease." (PMID 27093923, 2016). "Consistent with the in vitro data, low NLRP3 mRNA expression in kidney biopsies was associated with a linear trend of higher risk of composite endpoint of doubling serum creatinine and end stage renal disease in patients with IgAN." (PMID 27093923, 2016). "TLR4/NLRP3 signaling has been implicated in fibrogenesis and progression to chronic kidney disease." (PMID 40869248, 2025). "Similarly, I/R induced-acute kidney injury has been shown to be associated with over-expression of NLRP3 is overexpressed in chronic kidney disease." (PMID 36238294, 2022). "The role of NLRP3 has been underlined in various causes of acute and chronic kidney diseases and NLRP3 inhibition or IL-1β blocking may protect from AKI and AKI to CKD transition." (PMID 34099830, 2021). "With aberrant Cx43 activity linked to activation of P2X7 and NLRP3, targeting aberrant Cx43 mediated hemichannel ATP release clearly represents a future therapeutic avenue for the treatment of chronic kidney disease and other conditions where inflammation appears to be the underlying pathology." (PMID 32450899, 2020). "Given the current understanding of NLRP3 in the regulation of inflammation, tubular epithelial cell injury and fibrosis, the possibility exists that NLRP3 may be associated with the progressive chronic kidney disease induced by IgAN." (PMID 27093923, 2016). "Diabetic kidney disease (DKD) is a primary cause of end-stage renal disease (ESRD), and while ferroptosis is known to contribute to DKD pathogenesis, the regulatory role of the NLRP3 inflammasome in this process remains elusive." (PMID 42196240, 2026). "The NLRP3 inflammasome is likely a target for treatment in chronic kidney disease; thus, it would be good to understand its full mechanism in kidney illness." (PMID 40027896, 2025). "Search keywords comprised ‘Chronic kidney disease’, ‘NLRP3 inflammasome’, ‘traditional Chinese medicine’, and their relevant synonyms/combinations." (PMID 40841164, 2025). "Studies using animal models have demonstrated the contribution of NLRP3 inflammasome activation to kidney inflammation, tubulointerstitial fibrosis, glomerulosclerosis, and progression of chronic kidney disease (CKD)." (PMID 41515921, 2025). "The AIM2/NLRP3 inflammasomes are also a key component in the development and progression of chronic kidney disease (CKD)." (PMID 40264103, 2025). "Persistent NLRP3 activation is linked to CKD progression and an increased risk of end-stage renal disease." (PMID 40529990, 2025). "Conversely, in chronic kidney disease, persistent endogenous stimuli (such as uric acid crystals and oxidative stress by—products) induce continuous activation of the NLRP3 inflammasome." (PMID 40877572, 2025).
chronic kidney disease (continued). "Conversely, in the progression of chronic kidney disease, the knockout of NLRP3 is accompanied by the downregulation of MMP9." (PMID 38992615, 2024). "NLRP3 is prominently present in macrophages and tubular epithelial cells, both playing crucial roles in chronic kidney disease (CKD) development." (PMID 38740765, 2024). "Irisin prevents VC in chronic kidney disease by inducing autophagy and inhibiting NLRP3-mediated pyroptosis in vascular SMCs." (PMID 38201929, 2023). "Evidence supports the crucial role of NLRP3 inflammasome activation in the transition of acute kidney injury to Chronic Kidney Disease (CKD), by promoting both inflammation and fibrotic processes." (PMID 36835594, 2023). "NLRP3 inflammasome activation promotes inflammation, tubular injury, and fibrosis and is involved in pathogenesis of chronic kidney disease." (PMID 37293263, 2023). "Increasing evidence support the concept that NLRP3 inflammasome activation contributes to acute and chronic kidney disease including DKD." (PMID 35048962, 2022). "It is therefore of interest that increasing evidence supports the concept that nucleotide-binding oligomerization domain-like receptor pyrin domain containing 3 (NLRP3) inflammasome activation contributes to acute and chronic kidney disease including DKD." (PMID 35048962, 2022). "AQP2 also acts as a downstream effector of inflammation; for example, the Nod-like receptor protein 3 (NLRP3)-induced inflammatory response can decrease AQP2 expression in chronic kidney disease (CKD)." (PMID 35386692, 2022). "Recently it has been observed that the NLRP3 protein is expressed at high levels in progressive chronic kidney disease (CKD)." (PMID 35531273, 2022). "The NLRP3 inflammasome is also activated in both acute and chronic kidney disease in mice and humans." (PMID 35784553, 2022). "Oxidative stress is closely related to the activation of the NLRP3 inflammasome, which provides a new pathogenesis theory for the occurrence and development of hyperuricemia in chronic kidney disease." (PMID 35382689, 2022). "The activation of the ROS/NLRP3/caspase-1 signaling pathway induced by oxidative stress can also lead to endothelial dysfunction and pyroptosis in chronic kidney disease (CKD)." (PMID 36304156, 2022). "The NLRP3 upregulation leads to unsolved inflammation and other pathological effects, contributing to aggravation of kidney injury and even transition to chronic kidney disease (CKD)." (PMID 34011928, 2021). "In kidney disease, the NLRP3 inflammasome has been shown to contribute to the progression of acute kidney injury, chronic kidney disease, and diabetic nephropathy." (PMID 34769294, 2021). "Several publications focused on the formation and activation of NLRP3 in chronic kidney disease (CKD)." (PMID 34904012, 2021). "It has previously been shown that NLRP3 via an inflammasome-independent role mediates renal injury and contributes to the progression of chronic kidney disease." (PMID 34769294, 2021). "The NLRP3 inflammasome is a mediator of inflammation and contributes to the progression of chronic kidney disease." (PMID 34281284, 2021). "On the other hand, NLRP3 inflammasome has been shown to contribute to a wide range of acute and chronic kidney diseases; the importance of NLRP3 inflammasome in renal pathologic abnormalities in PE pathology is not well-understood." (PMID 32161574, 2020). "While IL-1β mediates podocyte injury and renal inflammation, NLRP3 is involved in the pathogenesis of chronic kidney disease." (PMID 33133213, 2020). "The NLRP3 inflammasome contributes to a wide range of acute and chronic kidney diseases via mechanisms that regulate inflammation, pyroptosis, apoptosis, and fibrosis." (PMID 32879619, 2020). "A large number of studies have also shown that the NLRP3 inflammasome is involved in the development of chronic kidney diseases (CKD)." (PMID 32039201, 2019).